CAPN3 (calpain 3)
Diseases named in the same sentence as CAPN3 in open-access papers (continued):
Sharing a sentence is not in itself a finding about the gene and the disease.
Becker muscular dystrophy (4 papers, 2012 to 2023). Becker muscular dystrophy (BMD) is a neuromuscular disease characterized by progressive muscle wasting and weakness due to degeneration of skeletal, smooth and cardiac muscle. "We studied muscle regeneration in 22 patients with LGMD2A with calpain 3 deficiency, in five patients with LGMD2I, with a secondary reduction in calpain 3, and in five patients with Becker muscular dystrophy (BMD) with normal calpain 3 levels." (PMID 22443334, 2012). "The morphology and level of regeneration in patients with two null alleles in CAPN3 were compared with those in patients with limb girdle muscular dystrophy type 2I (LGMD2I) and patients with Becker muscular dystrophy (BMD), who clinically and morphologically resemble patients with LGMD2A." (PMID 22443334, 2012).
muscular disease (4 papers, 2013 to 2025). Myopathy is a peripheral nervous system disease consisting of any abnormal condition or disease of the muscular tissues; commonly designates a disorder involving skeletal muscle. "Genomic DNAs from 401 adult individuals without muscular disease were analyzed for the presence of the CAPN3 c.348C>A mutation." (PMID 28103310, 2017).
Bethlem myopathy (3 papers, 2018 to 2022). A usually autosomal dominant inherited movement disorder caused by mutations in the COL6A1, COL6A2, and COL6A3 genes. "Autosomal dominant LGMDs represent about 10–15% of LGMDs and include disorders due to defects of DNAJB6, transportin-3 (TNPO3), HNRNPDL, Calpain-3 (CAPN3), and Bethlem myopathy." (PMID 35309568, 2022).
Atrophy (2 papers, 2021 to 2023). Any weakening or degeneration, especially through lack of use. "In addition, several studies revealed that calpain-3 levels are decreased in different atrophy conditions suggesting a unique or even contrary role of calpain-3 as compared to that of calpain-1/2, whose expression is increased in various atrophy conditions." (PMID 34572540, 2021). "In addition to CAPN3, we evaluated the levels of TNF-α and NF-κB to assess the responses of catabolic metabolism to the treatments used in the STZ-induced atrophy model." (PMID 38020198, 2023).
centronuclear myopathy (2 papers, 2020 to 2021). Centronuclear myopathy (CNM) is an inherited neuromuscular disorder characterized by clinical features of a congenital myopathy and centrally placed nuclei on muscle biopsy. "Proband B2, besides having two deep intronic variants in the CAPN3 gene, has also a novel mutation in the CCDC78 gene, related to centronuclear myopathy." (PMID 34720847, 2021).
distal myopathy (2 papers, 2020 to 2022). Distal myopathy refers to a group of muscle diseases which share the clinical pattern of predominant weakness and atrophy beginning in the feet and/or hands. "A distal myopathy panel may also want to include traditional LGMD genes CAPN3 and CAV3 as these can also result in a distal myopathy phenotype." (PMID 36313509, 2022).
eosinophilia (2 papers, 2008 to 2018). "However these authors concluded that some eosinophilia of mdx muscle is independent from perforin-mediated processes and that it may be suggested that a similar mechanism of calpain 3 could act in this process." (PMID 19015733, 2008).
liposarcoma (2 papers, 2011 to 2014). A usually painless malignant tumor that arises from adipose tissue. "Specifically, it was found that the mice with the mutation in Dystrophin, Dysferlin and Calpain-3 were susceptible to spontaneous formation of rhabdomyo-, fibro-and liposarcomas derived from skeletal muscle tissue 1–4 (reviewed in 5)." (PMID 24341522, 2014). "Here we show that mutations in muscular dystrophy genes (Dmd, Dysf, Capn3, Large) lead to the spontaneous formation of skeletal muscle-derived malignant tumors in mice, presenting as mixed rhabdomyo-, fibro-, and liposarcomas." (PMID 21533183, 2011).
Autosomal dominant limb-girdle muscular dystrophy (1 paper, 2025). "Clinical exome analysis was performed for late-onset Gitelman syndrome, which incidentally revealed a germline heterozygous mutation in CAPN3 (CAPN3(NM_000070.3):c.1466G > A; p.(Arg489Gln)) responsible for autosomal dominant limb girdle muscular dystrophy." (PMID 40520344, 2025).
autosomal dominant neovascular inflammatory vitreoretinopathy (1 paper, 2022). "This family of disorders includes forms of limb-girdle muscular dystrophy and autosomal dominant neovascular inflammatory vitreoretinopathy (ADNIV), which are caused by mutations in calpain-3 and calpain-5, respectively." (PMID 36385755, 2022).
Gitelman syndrome (1 paper, 2025). Gitelman syndrome (GS), also referred to as familial hypokalemia-hypomagnesemia, is characterized by hypokalemic metabolic alkalosis in combination with significant hypomagnesemia and low urinary calcium excretion. "However, this case highlights a rare association of possible functional Gitelman syndrome with autosomal dominant calpainopathy and opens research avenues to explore the intricate molecular interactions of calpain 3 with various transport channels in the renal tubules." (PMID 40520344, 2025).
hepatoma (1 paper, 2020). "The ethyl acetate extract of A. camphorata was shown to induce the activation of calpain-3 (CAPN-3) and caspases-12 (CASP-12) by increasing the level of Ca2+ in the cytoplasm of Hep3B cells and further induced the apoptosis of hepatoma cells." (PMID 32932919, 2020).
injury (1 paper, 2019). Damage inflicted on the body as the direct or indirect result of an external force, with or without disruption of structural continuity. "In addition, application of COE inhibited the induction of the proinflammatory cytokines and calpain-3 on dorsal root ganglion neurons in a spared nerve injury rat model." (PMID 31316578, 2019).
McArdle disease (1 paper, 2010). "This includes PYGM-deficiency (McArdle disease); lack of AMPD1, which causes metabolic myopathy in humans; and loss-of-function mutations in the CAPN3 gene that have been associated with limb-girdle muscular dystrophy type 2A (LGMD2A)." (PMID 20175888, 2010).
myotonic dystrophy type 2 (1 paper, 2025). Myotonic dystrophy type 2 (MD2), also known as proximal myotonic myopathy, is a very rare genetic multi-system disorder of late childhood or adult-onset characterized by mild myotonia, muscle weakness, and rarely cardiac conduction disorders. "Myotonic dystrophy type 2 (MIM #602668) and a common pathogenic variant: c.550delA (NM_000070.3) in the CAPN3 gene were excluded." (PMID 40529812, 2025).
pancreatic ductal adenocarcinoma (1 paper, 2021). An infiltrating adenocarcinoma that arises from the epithelial cells of the pancreas. "The cancer stem cell-like features of pancreatic ductal adenocarcinoma are maintained by the autocrine stimulation of extracellular interferon-stimulated gene 15 (ISG15), which is modulated by TRIM29 via Calpain-3 (CAPN3)-mediated posttranslational degradation." (PMID 34988104, 2021).
progressive muscular dystrophy (1 paper, 2025). "CAPN3 KO mice exhibit progressive muscular dystrophy with abnormal sarcomere organization, misaligned thick filaments, and disorganized mitochondria." (PMID 40280419, 2025).
sarcoma (1 paper, 2011). A usually aggressive malignant neoplasm of the soft tissue or bone. "Thus, additional loss of both dysferlin and calpain-3 in dystrophin-deficient mdx mice dramatically reduced sarcoma latency." (PMID 21533183, 2011). "Indeed, also Capn3 −/− mice developed skeletal muscle-derived sarcomas at an incidence of 5%." (PMID 21533183, 2011). "The combined effect of Dmd −/− Capn3 −/− in double-knockout mice, which also presented with a severe MD-phenotype leading to a shortened life-span of ∼13 months (R.B., manuscript in preparation), resulted in spontaneous sarcoma-formation in 44% of the animals with a mean-age of onset of ∼390 days." (PMID 21533183, 2011). "Lesions of the Nf1 gene (exons 23 and/or 56) were more frequently found in Dmd −/− (34%) and Dmd −/− Dysf −/− sarcomas (31%) as opposed to Dysf −/− (14%) or Dmd −/− Capn3 −/− (18%)." (PMID 21533183, 2011). "While the spontaneous occurrence of RMS has been previously reported in mdx mice and in addition in mice deficient of α-sarcoglycan (Sgca −/−, a model for the human LGMD2D), this is the first report of sarcomas in mice lacking dysferlin, calpain 3, or Large." (PMID 21533183, 2011).
Stillbirth (1 paper, 2023). Death of the fetus in utero after at least 22 weeks of gestation. "The calpain 3 (CAPN3) gene was associated with 24 QTLs/traits including bovine respiratory disease susceptibility, length of productive life, somatic cell score, fertility traits (calving ease, daughter pregnancy rate, and stillbirth), and udder traits." (PMID 37512987, 2023).
urinary bladder tumors (1 paper, 2010). "If our results are validated by other studies, Capn3 will definitely appear to play an important role in the molecular pathway of bovine urinary bladder tumors." (PMID 20421977, 2010). "Thus, the presence of calpain 3 mRNA and protein is a characteristic feature of these urinary bladder tumors." (PMID 20421977, 2010).
urothelial bladder cancer (1 paper, 2010). "The role of the Capn3 protein in urothelial bladder cancer still remains to be elucidated." (PMID 20421977, 2010).
vitiligo (1 paper, 2022). Generalized well circumscribed patches of leukoderma that are generally distributed over symmetric body locations and is due to autoimmune destruction of melanocytes. "CAPN3 overexpression was found in the skin of vitiligo vulgaris Mexican patients." (PMID 35406685, 2022).
weakness (1 paper, 2024). "In Austria, the most frequent cause of limb-girdle muscular weakness and hereditary myopathy were pathogenic variants in CAPN3, FKRP, ANO5, DYSF, SGCA." (PMID 38758368, 2024).
myopathy (14 papers, 2010 to 2025). A disease of the muscle in which the muscle fibers do not function properly. "Remarkably, whole-exome sequencing only revealed the c.1478G>A (p.Arg493Gln) mutation in CAPN3 as a potential explanation for the myopathy of our patients." (PMID 39703226, 2024). "Thirty cases each of BMD, CAPN3, inflammatory myopathy, and normal controls were chosen for comparison to the DYSF cases." (PMID 35135626, 2022). "GNE, DYSF, and CAPN3 are the three major genetic contributors to these myopathies in the Indian subcontinent." (PMID 33250842, 2020). "DYSF gene is much larger than some of the other genes such as GNE and CAPN3, the other two most prevalent myopathy forms in this study." (PMID 33250842, 2020). "We tested several candidate peptides based on their co-occurence with CAPN3 or myopathy in PubMed abstracts, and found some of them to be cleaved by CAPN3 confirming the predictive potential of the motif." (PMID 20694146, 2010). "Patients with ANO5 variants exhibited significantly later onset and shorter disease duration compared to CAPN3 and DYSF patients, emphasizing the relatively indolent course and late presentation of ANO5-related myopathy." (PMID 40870035, 2025). "The inflammatory myopathies had significantly higher numbers of CD20+ cells compared to controls (p = 0.05), and DM cases had significantly more CD20+ cells compared to normal controls (p = 0.002), BMD (p = 0.013) and CAPN3 (p = 0.005) cases." (PMID 35135626, 2022).
tumor (12 papers, 2010 to 2024). "Mice with mutations in the Dystrophin (DMD), Calpain-3 (LGMD2A) or Dysferlin (LGMD2B) genes are susceptible to malignant tumours originating from the skeletal muscles 1–4 (reviewed in 5)." (PMID 24341522, 2014). "Combined loss of dystrophin and dysferlin, as well as dystrophin and calpain-3, leads to accelerated tumor formation." (PMID 21533183, 2011). "In order to learn whether other MD-genes, which are not directly related to dystrophin, might also suppress tumor formation, we studied mice lacking dysferlin (DysfSJL mutation; Dysf −/−), calpain-3 (Capn3 −/−; knockout), or Large (Largemyd mutation; Large −/−)." (PMID 21533183, 2011). "In order to test if dystrophin, dysferlin and calpain-3 have tumor-suppressor effects in vivo, we generated double-mutant mouse lines, i.e. dystrophin-deficient (mdx) mice with additional lack of either dysferlin (Dmd −/− Dysf −/−) or calpain-3 (Dmd −/− Capn3 −/−)." (PMID 21533183, 2011).
cancer (8 papers, 2011 to 2024). A tumor composed of atypical neoplastic, often pleomorphic cells that invade other tissues. "Interestingly, mice lacking dystrophin or dystrophin-associated proteins including dysferlin, α sarcoglycan, calpain-3, and Large form spontaneous malignant tumors with muscle differentiation." (PMID 30575736, 2018). "Our results indicated that higher gene expression levels of RELA were positively correlated with increased IC50 values of cancer therapy drugs, while UBA2, TRIM28, TRIM27, and CAPN3 showed opposite correlations." (PMID 38407971, 2024).
neuromuscular disease (6 papers, 2016 to 2025). "Limb Girdle Muscular Dystrophy R1 (LGMDR1) is an autosomal recessive neuromuscular disease caused by mutations in the calpain-3 (CAPN3) gene." (PMID 38561828, 2024). "Targeted NGS performed in Patients 1 and 2 and exome sequencing in Patient 1 confirmed the presence of a homozygous CAPN3 c.1992 + 2T>G variant and did not identify pathogenic variants in genes related with other neuromuscular disease." (PMID 31612648, 2019). "Limb-girdle muscular dystrophy type 2A (LGMD2A) is a neuromuscular disease caused bymutations in the gene encoding calpain 3 (CAPN3), a nonlysosomal cysteine protease necessaryfor normal muscle function and regeneration (Refs 1,2)." (PMID 27055500, 2016).
genetic disorder (2 papers, 2008 to 2012). "Limb-girdle muscular dystrophy type 2A (LGMD2A) is a recessive genetic disorder caused by mutations in calpain 3 (CAPN3), a muscle-specific, calcium-dependent cystein protease." (PMID 19015733, 2008). "LGMD2A is a recessive genetic disorder caused by mutations in calpain 3 (CAPN3)." (PMID 23060854, 2012).
infection (2 papers, 2016 to 2018). The state of being infected such as from the introduction of a foreign agent such as serum, vaccine, antigenic substance or organism. "Infection with Capn3-shRNA lentivirus caused a70% reduction of Capn3 protein in C2C12 differentiated myotubes, as assessed by Westernblot (P ≤ 0.01)." (PMID 27055500, 2016).
autosomal dominant disease (1 paper, 2025). Autosomal dominant form of disease. "Recently, growing evidence implicates heterozygous CAPN3 variants in autosomal dominant disease (LGMDD4), with pathogenic mechanisms still incompletely understood." (PMID 41373542, 2025).
CAPN3 also shares sentences with these, for which no sentence is quoted: facioscapulohumeral muscular dystrophy (5 papers); sarcoglycanopathies (5); prostate carcinoma (4); myositis (3); glioma (2); Immunodeficiency (2); myotonic dystrophy (2); rhabdomyolysis (2); sporadic inclusion body myositis (2); systemic sclerosis (2); tibial muscular dystrophy (2); type 2 diabetes (2); albinism (1); alpha sarcoglycanopathies (1); antisynthetase syndrome (1); atrial fibrillation (1); Batten disease (1); Brain atrophy (1); brain tumor (1); Brody disease (1); cardiac arrhythmia (1); congenital muscular dystrophy (1); Congenital muscular dystrophy type 1A (1); congenital myopathy (1); deafness (1); dermatomyositis (1); dystroglycanopathies (1); eosinophilic myositis (1); External ophthalmoplegia (1); Facioscapulohumeral dystrophy (1).
A further 37 diseases each share a sentence with CAPN3 in 1 paper.